IL10 (interleukin 10)
Diseases named in the same sentence as IL10 in open-access papers (continued):
Sharing a sentence is not in itself a finding about the gene and the disease.
cancer (continued). "Neutrophils secrete a variety of cytokines such as interleukin-2, interleukin-10, which is beneficial to cancer progression." (PMID 31921649, 2019). "Owing to the production of soluble factors in cancer, such as interleukin-10 (IL-10), tumor necrotic factor (TNF), transforming growth factor (TGF)-β, and VEGF, the function and action of immune cells are blocked." (PMID 30871059, 2019). "Amoeboid cancer cells induce macrophages that are CD206highCD163highHLA-DR+CD86low and produce IL-10 and TGF-β." (PMID 30712866, 2019). "Reports demonstrate constitutive production of IL-10 in vitro from several cancer cell lines including colon, lung, and skin carcinoma." (PMID 31681327, 2019). "On the front of cancer cells, both H460R and A549R cells showed a significant increase in the mRNA level of Src, IL-4, IL-10 and MIF as compared to their parental counterparts." (PMID 31036057, 2019). "Mo-DCs from cancer patients presented decreased expression of DC maturation markers, decreased ability to induce allogeneic lymphocyte proliferation, and increased IL-10 secretion." (PMID 31827382, 2019). "IL-10 exerts a wide spectrum of regulatory activities in the immune and inflammatory response and even in cancer." (PMID 31885668, 2019). "High levels of IL10 can lead to various pathologies, and IL10 antagonists have the potential to be used against chronic infection or cancer." (PMID 31695803, 2019). "IL-10 is one of the most significant anti-inflammation cytokines produced during infectious diseases and cancer." (PMID 31582901, 2019). "High serum levels of the “immunosuppressive” cytokines in blood, like interleukin (IL)-6 and IL-10, are found to be correlated with poor prognosis, cancer stage and disease progression." (PMID 30232514, 2019). "Studies on mice deficient of key markers of Tregs, including IL-10, CTLA-4, GITR, or PD-1 that develop severe immune-related disorders indicate that these molecules are crucial for Treg function in a cancer setting." (PMID 31134056, 2019). "Interleukin 10 (IL-10), an immunosuppressive cytokine, is a regulatory element required for angiogenesis in many cancers." (PMID 30871059, 2019). "Poly I:C-primed MSCs have been found previously to induce a net increase in IL-10 concentration in media from poly I:C-primed MSCs and cancer cells." (PMID 29615127, 2018). "Elevated levels of IL-10 are commonly correlated with high-grade lesions and cancer condition, and its immunosuppressive roles have been reported countless times, what are probably induced by HPV E2 protein activity." (PMID 29854832, 2018). "After 2 days of co-culture, monocytes exposed to cancer cell lines showed markedly upregulated expression of M1-associated (TNF-α, IL-1β), M2-associated (CCL13, CD206), Mreg-associated (IL-10, TGF-β), and angiogenesis associated (MMP9, VEGF) genes." (PMID 29668679, 2018). "These cells are rich in high-grade carcinoma samples, suppress CTL and NK cell activities, and support cancer progression through cytokine synthesis, such as IL-10 itself and TGF-β." (PMID 29854832, 2018). "IL-10 exhibits a dual role during cancer development, inducing both cancer-promoting (immunosuppressive) and cancer-inhibiting (anti-angiogenic) effects." (PMID 29552317, 2018). "Tumors with a good-TiME signature were enriched for partially exhausted CD8+ T cells that have enhanced capacity to release IFN-γ, activated pDC, HLA-DR+ cancer cells, and decreased numbers of IL-10– and IL-17–releasing Tregs and PD-L1+ TAM." (PMID 29618661, 2018). "Inflammatory cytokines released by various cancer entities, like IL-3, IL-6, and IL-10, are capable of stimulating megakaryocytes proliferation, which can produce platelets." (PMID 30643825, 2018). "Consistent with previous findings, our observations revealed that AS-IV clearly ameliorated cancer-associated inflammation, decreased the expression of inflammatory factors such as TGF-β and IL-10, and suppressed M2 macrophage polarization." (PMID 30157903, 2018).
cancer (continued). "IL-10 production by spleen cells of IL-23R KO mice remained at a relatively constant level even as lesions advanced to cancer, although at this latter time point IL-10 production by spleen cell of wildtype mice increased." (PMID 29664967, 2018). "Elevation of CD163, PD-L1 and IL-10 expression on CD14+ monocytes from PBMCs of cancer patients was observed as compared to those from healthy donors." (PMID 30563569, 2018). "During Cancer, the marked increase in IL10 production has been noted in blood samples of various cancer patients, where an average concentration of 0.01ng/ml has been recorded in various protein expression studies." (PMID 30183728, 2018). "Cancer cell adhesion to IL-6/IL-10 stimulated blood and lymphatic endothelial cells (EC) was investigated." (PMID 29256156, 2018). "This is because M2 is a prime source for the production of IL10 cytokine that has an important role in positively regulating the proliferation of the Cancer (C) cells." (PMID 30183728, 2018). "Some cancer cells express more IL-10, which is correlated with cancer progression from the radial to vertical growth phase as well as with the development of metastatic competence." (PMID 28143527, 2017). "Cancer cells secrete anti-inflammatory cytokines such as IL-4, IL-10, and TGF-β and induce systemic inflammation and suppress lymphocyte function." (PMID 28938679, 2017). "Immunosuppressive factors, such as TGF-β1 and IL-10, were reported to alter NK cell functions in cancers." (PMID 28384121, 2017). "IL-27 induces inhibitory molecules including PD-1, Tim-3, LAG-3, TIGIT, and IL-10, which overlap with the mediators of T cell exhaustion, in chronic viral infections and cancer." (PMID 28545567, 2017). "The expressions of IL-4, IL-10 and IL-13 were significantly decreased in the metformin-treated cancer cells compared to the control cells." (PMID 28157701, 2017). "These polarizations are adjusted by cytokines, such as macrophage-colony-stimulating factor (M-CSF), transforming growth factor (TGF)-β, interleukin (IL)-6 and IL-10 in the cancer microenvironment." (PMID 28583114, 2017). "Our study revealed that patients with active cancer had higher baseline plasma IL-10 levels and patients with higher baseline IL-10 had higher 14-, 28- and 90-day mortality rates." (PMID 28692671, 2017). "In accordance with our in vitro experiments using IL-1R8-knockdown cancer cells, we observed that MMTV-neu/IL-1R8−/− TAMs showed reduced expression of markers associated with an M2-like phenotype, in particular CD206, YM1, IL-10." (PMID 28533483, 2017). "Gene expression of PD-1 as well as CTLA-4, CD25, CD28, Foxp3, TGF-β and IL-10 was increased in most cancer patients compared to that in healthy adults." (PMID 28881603, 2017). "Although the relationship between IL-10 and cancer has been extensively studied, the exact role of IL-10 in cancer is still elusive, since IL-10 have both cancer-promoting and -inhibiting properties." (PMID 28977953, 2017). "TAMs also inhibit the immune reaction of CD8+ T-cells against cancer cells by producing IL-10 and TGFβ." (PMID 28178994, 2017). "The interleukin-10 (IL-10) is a multifunctional immunosuppressant cytokine that is reported to be related to cancer onset and development." (PMID 28410223, 2017). "IL-12p70 is an important cytokine for stimulating naive T cells for Th1 polarization to benefit cancer treatment, but IL-10 is the main inhibitory cytokine for cancer treatment." (PMID 28266813, 2017). "In THP-1 cells, the potential of CLE to increase IL-10 levels will facilitate a decrease in pro-inflammatory cytokine levels, a decrease in malignant cell progression and possibly alleviate the cancer cachectic syndrome." (PMID 28764778, 2017). "The IL-10 pathway has been intensively studied for its role in T cell dysfunction in chronic viral infections and cancer." (PMID 28545567, 2017).
cancer (continued). "Previous studies showed that STAT3 mediates the expression of vascular endothelial growth factor (VEGF), IL-6, and IL-10 in many cancer types, which induce T cell tolerance through inhibition of DC differentiation and maturation." (PMID 28611673, 2017). "IL-10 in cancer has been reported to exhibit differential effects that seem to be contradictory in some cases." (PMID 28626727, 2017). "Whatever the case, the results warrant future studies exploring CD5 targeting to improve the efficacy of currently available immunotherapeutic approaches against cancer such as IL-10, TGF-β inhibitors or IL-2/anti-IL-2 mAb immunocomplexes." (PMID 29296231, 2017). "In other studies in patients with cancer, associations have been shown between appetite loss and IL-1β, IL-6 and IL-8 and with gene polymorphisms coding for TNF-α, IL-1β, and IL-10." (PMID 28542626, 2017). "This is reasonable because the serum concentrations of IL-10 in cancer patients and the secretion of IL-10 by cancer cell lines are in the range of 0.01, 0.1, and 1 ng/ml." (PMID 28234961, 2017). "Cancer patients often have increased levels of serum IL-10; and increased levels of IL-10 often indicate poor prognosis." (PMID 28810829, 2017). "As an anti-inflammatory cytokine, IL-10 participates in the development of various diseases, such as chronic infection, kidney disease, cancer, and cardiovascular diseases." (PMID 28651598, 2017). "While it is probable that elevated IL-10 levels are related to poor prognosis in cancer patients admitted to the ICU, further studies need to be done in this area." (PMID 28692671, 2017). "IL-10 can be considered an immunosuppressive cytokine, promoting cancer escape from immune surveillance." (PMID 29089667, 2017). "IL-10 is not only produced by various immunocompetent cells but also by human cell lines derived from carcinomas such as colon, kidney, and breast." (PMID 29162930, 2017). "IL-10 has been reported to be a major factor inhibiting the differentiation of DCs from monocytes in cancer." (PMID 27833081, 2016). "Interleukin-10 (cytokine synthesis inhibitor factor, CSIF) is an important cytokine produced by several cells such as normal and neoplastic B cells, macrophages, T cells and some cancer cells." (PMID 27547238, 2016). "Some recent studies have shown the relationship between cancers and inflammatory factors, such as IL-6 and IL-10." (PMID 27230680, 2016). "In OSCC tissues, IL-10+ and IL-4+ macrophages were predominantly seen in the cancer nests, and some positive signals were also found in cancerous epithelial tissues." (PMID 28053372, 2016). "IL-10 in the liver modulates the inflammatory response and protects from collateral injury in chronic renal disease, colonitis, and cancer." (PMID 26475448, 2016). "It is well known that IL-2 is an important regulator for NK cell activation, and TGF-β, IDO, and IL-10 are crucial inflammatory mediators for the direct or indirect inhibition of NK cells and the initiation and progression of cancers." (PMID 27034590, 2016). "Accordingly, immunotherapies that interfere with CD95–CD95L axis and IL-10 production should be part of the arsenal used to re-establish immune response in cancer patients." (PMID 27853178, 2016). "In various human cancers malignant cells and host infiltrating cells express and secrete a range of Th1, Th2, and Th17 cytokines (IL-1β, IL-2, IL-4, IL-6, IL-10, IL-17, and IFN-γ) and TGF-β." (PMID 27777963, 2016). "Since IL-10 is an immunosuppressive cytokine that enables cancer cells evade the host immune system, these effects of HBZ are implicated in evasion of host defense to infected cells." (PMID 26735971, 2016). "To study the role of secreted IL10 in the proliferation of cancer cells, we collected the conditioned media of A549 cells treated with EGF in serum-free media for 24 h." (PMID 26956044, 2016).
cancer (continued). "Laricitrin decreases expression of IL-10 in cancer-conditioned DCs, and subsequently switches CD4+ T cell response from Th2 to Th1 in vitro and in vivo." (PMID 27833081, 2016). "Mast cells play a key role in the pathogenesis of cardiovascular diseasesand cancers via secreting a variety of cytokines includingTNF-α, IL-3, IL-4, IL-5, IL-6, IL-10, IL-13, IL-14 and IL-16." (PMID 26625310, 2016). "Immunohistochemical staining of IL-10 was increased in malignant tumors compared with benign tumors (P=0.0128)." (PMID 25624918, 2015). "A significant decrease in the invasion ability of cancer cells confronted with IL-10-stimulated macrophages was observed upon EGFR silencing, even when comparing with AGS cells transfected with Lipofectamine only." (PMID 26043921, 2015). "Subgroup analysis of solid tumors and hematological malignancies was conducted to identify the effect of IL–10 on different types of cancer." (PMID 26440936, 2015). "Knowing that C3-1-TAg mice exhibit hormone-dependent carcinogenesis, and that neutrophils robustly interact with estrogen and IL-10, the relationships between microbes, hormones, immunity and cancer are a key topic for future studies." (PMID 25831236, 2015). "In contrast, IL-8 and IL-10 concentrations were significantly lower in cancer patients than in healthy controls." (PMID 26486258, 2015). "Taking into account that EGFR is required for IL-10- and LPS-stimulated macrophage-mediated invasion, we evaluated if both macrophage populations differently affected cancer cell EGFR signalling." (PMID 26043921, 2015). "In previous studies, high level of IL–10 was reported to correlate with poor survival of some cancer patients, while some other studies provided opposite results." (PMID 26440936, 2015). "Our results show that IL-10-stimulated macrophages are more efficient in promoting in vitro cancer cell invasion and migration." (PMID 26043921, 2015). "In the present study, LPS- and IL-10-stimulated macrophages induced cancer cell cytoskeleton reorganization and the formation of motility-associated structures, such as lamellipodia and filopodia." (PMID 26043921, 2015). "In this context, several recent clinical studies showed that IL-10 was an immune suppressor of different cancers that able to lead an adverse outcome in terms of immune tolerance." (PMID 26060426, 2015). "Here, we conducted a meta-analysis to assess the prognostic impact of serous IL–10 expression in cancer patients." (PMID 26440936, 2015). "Nevertheless, soluble molecules produced by IL-10-stimulated macrophages were significantly more efficient in inducing cancer cell migration than those released by LPS-stimulated macrophages." (PMID 26043921, 2015). "Here, we performed this meta-analysis to test OS and DFS as outcomes in cancer patients with known serum IL–10 levels." (PMID 26440936, 2015). "In previous cancer studies, high level of IL–10 was reported to correlate with poor clinical outcome, while some others suggested IL–10 as a beneficial factor in cancer prognosis." (PMID 26440936, 2015). "Immunohistochemical staining of IL-10 was more intense in malignant tumors compared with benign tumors (P=0.0128)." (PMID 25624918, 2015). "Some studies have reported that overexpression of serous IL–10 is correlated with worse outcome in patients with malignant tumor." (PMID 26440936, 2015). "Overall these results indicate that IL-10-stimulated macrophages are more efficient than LPS-sitmulated macrophages in inducing cancer cell migration." (PMID 26043921, 2015). "First, we show that high level of serum IL–10 has a tight correlation with poor prognosis in cancer patients, which suggests that IL–10 is a promising biomarker for the evaluation of disease progression and survival time." (PMID 26440936, 2015). "Because cancer cells can secrete IL-10, a role in the escape of immunosurveillance has been ascribed to IL-10 in tumors." (PMID 26510188, 2015).
cancer (continued). "The presence of Galardin resulted in a slight, although statistically significant, decrease in the ability of IL-10-stimulated macrophages to induce cancer cell-mediated angiogenesis." (PMID 26043921, 2015). "Following these discoveries, further clinic trials on IL–10 antagonist is imperatively needed to detect the clinical response in cancer patients." (PMID 26440936, 2015). "C4-27z and C4opt-27z CAR T lymphocytes secreted low, but reliably detectable levels of Th-2 cytokines, including IL-4 and IL-10, in response to FRα+ cancer cells although the response was considerably Th-1 biased." (PMID 26359629, 2015). "For instance, il1b, which promotes early cancer angiogenesis, was significantly upregulated while anti-tumor cytokines, il4, il6, il8, il10, il12, and tnfa, all showed significant downregulation." (PMID 25828472, 2015). "TGF-β and IL-10, for example, are two pleiotropic factors released by numerous cancers that have generalized anti-inflammatory properties." (PMID 26000958, 2015). "As such, the higher proteolytic activity of IL-10-stimulated macrophages parallels with their higher ability to stimulate cancer cell invasion and angiogenesis." (PMID 26043921, 2015). "In the presence of CM from IL-10-stimulated macrophages, cancer cells described wider trajectories and travelled significantly longer distances in comparison to cancer cells stimulated with CM from LPS-stimulated macrophages (CM(LPSmac))." (PMID 26043921, 2015). "The suppression of anti-inflammatory IL-10 was observed in the colorectal M2 macrophages, which occurred concomitantly with low expression levels of pro-inflammatory cytokines, prior to carcinoma formation." (PMID 25434400, 2015). "Advanced cancer patients had similar numbers of circulating myDC to cancer-free patients and healthy individuals, and secreted similar levels of IL-1β, IL-6, IL-10, IL-12 and IL-23." (PMID 23901045, 2014). "Following five days of incubation, the surface CD14 expression was determined, and it was found that PAO and CD45i reversed cancer cell-mediated TADC differentiation in the IL-10, A549, MDA and SW480 groups." (PMID 25013476, 2014). "IL-12 and IL-10 seem to be affected by various modes of tobacco exposure and inflammation also affects median survival of cancer patients." (PMID 25177683, 2014). "On the other hand, anti-inflammatory IL-10 has been suggested to have an antiangiogenic role in several cancer models." (PMID 24901008, 2014). "We found that levels of IL-6, IL-8, and IL-10 were significantly higher (up to 3 times) in cancer patients than in healthy individuals." (PMID 24849506, 2014). "The variations in plasma IL-10 concentrations were observed in the patients with differing stages of cancer." (PMID 24765208, 2014). "Several carcinoma tissues and cultured cancer cell lines demonstrate the expression of Foxp3 and IL-10, suggesting that cancer cells induce the Treg cell-like immunoregulatory milieu to evade immunosurveillance." (PMID 25132998, 2014). "A highly immunosuppressive environment with increased numbers of Treg, MDSC, and suppressive cytokines such as IL-10 and TGF-β is strongly associated with increased risk of cancer." (PMID 24639678, 2014). "For several types of cancers, elevated serum levels of TGF-β or IL-10 have been reported to be associated with worse prognosis [reviewed in Ref." (PMID 24860567, 2014). "The albumin level, white blood cell count, and concentrations of PGE2, TGF-β, and IL-10 are important immunological indicators for cancer patients." (PMID 25267108, 2014). "It seems that the influencing roles of inflammation-activated cancer cells in the frequencies of CD19+CD24hiCD27+ and CD19+IL-10+ B cells are associated with the severities of inflammation." (PMID 25381811, 2014). "(c) Mesothelin-specific CD4+ T cell response is directly inhibited by elevated IL-10 in cancer patients." (PMID 24520352, 2014).